STK25 (serine/threonine kinase 25)
Description:
Oxidant stress-activated serine/threonine kinase that plays a role in metabolic homeostasis, neuronal polarization, cell migration, Golgi organization, apoptosis or innate immunity. Targets to the Golgi apparatus where it appears to regulate protein transport events, cell adhesion, and polarity complexes important for cell migration. Part of the striatin-interacting phosphatase and kinase (STRIPAK) complexes. STRIPAK complexes have critical roles in protein (de)phosphorylation and are regulators of multiple signaling pathways including Hippo, MAPK, nuclear receptor and cytoskeleton remodeling. Different types of STRIPAK complexes are involved in a variety of biological processes such as cell growth, differentiation, apoptosis, metabolism and immune regulation. Functions as an inhibitor of the PKA pathway by affecting phosphorylation of the PRKAR1A regulatory subunit, which in turn suppresses the kinase activity of the catalytic subunit. Positively regulates the TLR signaling by directly phosphorylating the transcription factor IRF5.
Synonyms: SOK1; YSK1
Tractability: Small molecule: a structure with a bound ligand is known; a high-quality ligand is known; it has a binding pocket of medium quality; it belongs to a druggable protein family. PROTAC: ubiquitination databases record sites on it; its protein half-life has been measured; a small molecule that binds it is known.
Target class: STE protein kinase group; STE protein kinase STE20 family; STE protein kinase YSK subfamily; Protein Kinase; Kinase; Enzyme
Gene: Protein-coding gene on chromosome 2 (241,492,670 to 241,509,730, reverse strand). Ensembl gene ENSG00000115694.
Subcellular location: Cytoplasm; Golgi apparatus
Gene Ontology:
Molecular function: protein binding; protein homodimerization activity; protein serine/threonine kinase activity; protein kinase activity; ATP binding; protein serine kinase activity
Biological process: cellular response to oxidative stress; establishment of Golgi localization; Golgi localization; Golgi reassembly; intrinsic apoptotic signaling pathway in response to hydrogen peroxide; negative regulation of cAMP/PKA signal transduction; positive regulation of stress-activated MAPK cascade; protein autophosphorylation; protein phosphorylation; intracellular signal transduction; response to oxidative stress; signal transduction
Cellular component: cytoplasm; extracellular exosome; FAR/SIN/STRIPAK complex; Golgi apparatus
Genetic constraint (gnomAD): Loss-of-function variants: 29 observed, 56.13 expected, observed/expected ratio (o/e) 0.52, 90% interval 0.38 to 0.7. The upper end of that interval is the gene's LOEUF score, 0.7, which puts it in group 2 of 6, group 1 being the genes least tolerant of losing a copy. Missense variants: 420 observed, 587.33 expected, observed/expected ratio (o/e) 0.72, 90% interval 0.66 to 0.77. Synonymous variants: 247 observed, 249.15 expected, observed/expected ratio (o/e) 0.99, 90% interval 0.89 to 1.1.
Homologues: Orthologues: chimpanzee STK25 (99% identical), mouse Stk25 (99% identical), dog STK25 (97% identical), guinea pig STK25 (96% identical), pig STK25 (95% identical), rat Stk25 (95% identical), macaque STK25 (91% identical), zebrafish stk25b (83% identical), zebrafish stk25a (78% identical), Drosophila melanogaster GckIII (63% identical). Paralogues in human: STK24 (73% identical), STK26 (68% identical), TNIK (42% identical), MAP4K4 (41% identical), MINK1 (41% identical), TAOK1 (38% identical), MAP4K3 (37% identical), STK10 (37% identical), TAOK3 (37% identical), STK4 (36% identical), STK3 (36% identical), MAP4K5 (36% identical), and 23 more.
Diseases named in the same sentence as STK25 in open-access papers:
STK25 is named in the same sentence as 49 diseases in open-access papers, as found by Europe PMC text mining. Sharing a sentence is not in itself a finding about the gene and the disease. The quoted sentences say what the papers report.
colorectal cancer (8 papers, 2018 to 2026). A primary or metastatic malignant neoplasm that affects the colon or rectum. "LIM domain kinase 1 (LIMK1), a novel β-catenin kinase highly expressed in colorectal cancer and associated with poor prognosis, promotes malignant progression through its interaction with STK25, which enhances cell proliferation and metastasis." (PMID 41614944, 2026). "The aim of this study is to investigate the role of STK25 in colorectal cancer (CRC) and to elucidate the underlying mechanisms." (PMID 29996891, 2018). "STK25 is a germinal-center kinase (GCK) III subfamily and is highlyexpressed in liver and colorectal cancer, suggesting the possibilityof STK25 as a prognostic marker for cancer." (PMID 38293943, 2024). "However, the function of STK25 in the colorectal cancer (CRC) microenvironment remains unclear." (PMID 40729594, 2025).
Insulin resistance (7 papers, 2017 to 2025). Increased resistance towards insulin, that is, diminished effectiveness of insulin in reducing blood glucose levels. "Taken together, these findings suggest that STK25 increases the susceptibility to ectopic lipid storage and meta-inflammation in the main tissues prone to diabetic damage under metabolic stress, resulting in whole-body glucose intolerance and insulin resistance." (PMID 28442507, 2017). "In skeletal muscle, the serine/threonine protein kinase 25 (STK25) is known to aggravate insulin resistance." (PMID 30258344, 2018). "Reciprocally, our studies showed that, compared with wild-type littermates, Stk25 knockout mice are protected against systemic glucose intolerance and insulin resistance induced by a high-fat diet." (PMID 27981357, 2017). "Reciprocally, Stk25 knockout mice are protected against high-fat diet-induced whole-body glucose intolerance and insulin resistance compared with their wild-type littermates." (PMID 28442507, 2017). "Indeed, we observed aggravated apoptosis in Stk25 transgenic pancreas, which probably contributed to the lost ability to increase insulin secretion in the context of insulin resistance." (PMID 28442507, 2017). "We previously showed that peripheral insulin resistance in high-fat-fed Stk25 transgenic mice compared to wild-type controls is accompanied by hyperinsulinaemia, suggesting that pancreatic β-cells could potentially increase insulin production in response to increased insulin demands." (PMID 28442507, 2017). ",58, 59, 60 We and other research groups also reported that, similarly to STK25, the inactivation of MST3 by genetic knockout or by ASO treatment protects mice against diet-induced insulin resistance and MASLD." (PMID 40024534, 2025). "In contrast to the in vivo inactivation of STK25 or MST3, we observed that the genetic knockout of MST4 in mice has no impact on the development of diet-induced MASLD, glucose intolerance, or insulin resistance." (PMID 40983918, 2025). "Taken together, these findings suggest that STK25 may regulate the shift in the metabolic balance from lipid use to lipid storage in several tissues prone to diabetic damage, contributing to the pathogenesis of whole body insulin resistance and type 2 diabetes." (PMID 27981357, 2017). "Suppression of STK25 abundance did not lead to consistent alterations in fasting blood glucose, plasma insulin, or the homeostasis model assessment score of insulin resistance (HOMA-IR), measured at several time points during the study." (PMID 40024534, 2025).
Hepatic steatosis (6 papers, 2020 to 2025). Steatosis is a term used to denote lipid accumulation within hepatocytes. "Together, in addition to inhibition of liver tumorigenesis, loss of STK25 in both HCC models substantially suppressed all the pathologic features of NASH, including hepatic steatosis, inflammation, and fibrosis." (PMID 34624527, 2022). "Furthermore, we found that STK25 mRNA and protein levels correlate with the severity of hepatic steatosis and lobular inflammation in human liver biopsies, and several common nonlinked SNPs in the human STK25 gene are associated with altered liver fat." (PMID 33170807, 2020). "We have previously demonstrated that Stk25–/– mice and mice treated with Mst3-targeting ASO are protected from the development of diet-induced MASLD as evidenced by decreased hepatic steatosis, lobular inflammation, and nutritional fibrosis." (PMID 40983918, 2025). "We found a significant positive correlation between the expression of STK25, MST3, and MST4 in human liver biopsies and the severity of MASLD assessed using MAS (i.e., MASLD activity score composed of the histological scores of hepatic steatosis, lobular inflammation, and ballooning degeneration)." (PMID 40983918, 2025).
hepatocellular carcinoma (5 papers, 2022 to 2025). A malignant tumor that arises from hepatocytes. "STK25 knockout in human hepatoma cells also blocked tumor formation and growth in a subcutaneous xenograft mouse model." (PMID 40024534, 2025). "We detected a significant increase in mitochondrial area and perimeter, without any change in the number of cristae per mitochondrial area, when comparing the hepatoma cells where STK25 was knocked out vs control cells." (PMID 40024534, 2025). "Consistent with our earlier observations, we detected a decreased volume of lipid droplets in hepatoma cells where STK25 was knocked out." (PMID 40024534, 2025). "Of note, STK25 knockdown induced a comparable inhibition of proliferation in sorafenib-naïve and sorafenib-resistant hepatoma cells." (PMID 40024534, 2025). "Second, STK25 knockout in human hepatoma cells blocked tumor formation and growth in a xenograft mouse model." (PMID 40024534, 2025). "The functional significance of STK25 silencing in human hepatoma cells was evaluated in vitro and in a subcutaneous xenograft mouse model." (PMID 40024534, 2025). "The in vitro silencing of STK25 in human hepatoma cells suppressed proliferation, migration, and invasion with efficacy comparable to that achieved by anti-HCC drugs sorafenib or regorafenib." (PMID 40024534, 2025). "Nonetheless, the combined analyses in liver biopsies from patients with HCC, human hepatoma cell line-derived xenograft model, and cultured human hepatoma cells performed in this study support the benefits of STK25 inhibition in human MASH-driven HCC." (PMID 40024534, 2025). "To further study the cell-autonomous mechanisms behind the tumor-mitigating effects of STK25 knockdown, we silenced this target in HepG2 hepatocellular carcinoma cells by a small interfering RNA (siRNA) approach." (PMID 34624527, 2022). "Finally, the in vitro silencing of STK25 alleviated tumorigenicity of human hepatoma cells by inhibiting proliferation, migration, and invasion." (PMID 40024534, 2025). "Notably, anti-tumorigenic activity was significantly enhanced when sorafenib or regorafenib treatment was combined with STK25 knockdown, and the silencing of STK25 had a similar impact in sorafenib-naïve and sorafenib-resistant hepatoma cells." (PMID 40024534, 2025). "In addition, we combined analyses in liver biopsies and a xenograft mouse model with mechanistic experiments in cultured hepatoma cell lines to characterize the role of human STK25 in the pathogenesis of HCC." (PMID 40024534, 2025). "Then, we preliminarily confirmed that STRN could reverse the effect of STK25 depletion through AMPK/ACC1 pathway, which suggested that STK25 enhances hepatocellular carcinoma progression through the STRN/AMPK/ACC1 pathway." (PMID 34986838, 2022). "Consistent with this, STK25 deficiency was shown to lead to a moderate, but significant, increase in liver mass in mice at 6–12 months of age; however, liver carcinomas were not identified in any of the animals." (PMID 34624527, 2022). "Importantly, in this study, we did not detect any alterations in the levels of MST3 or MST4 in STK25-deficient mouse livers or human hepatoma cells." (PMID 40024534, 2025).
Obesity (5 papers, 2017 to 2025). Accumulation of substantial excess body fat. "Our previous research has revealed that Stk25 knockout mice are protected against hepatic, renal, and skeletal muscle lipotoxicity in connection to obesity." (PMID 40983918, 2025). "Consistent with the “whitening” of BAT in obesity, we observed adipocytes with a “white-like” appearance, characterized by large lipid droplets, in the BAT sections from both high-fat diet-fed wild-type mice and mice deficient in either STK25 or MST3." (PMID 40983918, 2025). "In search of novel targets that control ectopic lipid deposition, we recently identified serine/threonine protein kinase 25 (STK25), a member of the sterile 20 kinase superfamily, as a critical regulator of lipotoxicity in the context of nutritional stress and obesity." (PMID 33170807, 2020). "In summary, this study unravels a role for STK25 in determining the susceptibility to diet-induced non-alcoholic fatty pancreas disease in mice in connection to obesity." (PMID 28442507, 2017). "Consistently, histological evaluation of the BAT from mice depleted of STK25 and MST3 revealed brown adipocytes with a condensed morphology and numerous small multilocular lipid droplets, suggesting protection against obesity-induced “whitening” of BAT." (PMID 40983918, 2025). "The objective of this study was to examine the in vivo effects of the silencing of two closely related STE20-type kinases STK25 and MST3, either alone or in combination, using a mouse model of high-fat diet-induced obesity." (PMID 40983918, 2025). "Dual inhibition of STK25 and MST3 in mice mitigates obesity-triggered lipotoxic injury to metabolic tissues and elevates indicators of BAT thermogenic capacity." (PMID 40983918, 2025).
type 2 diabetes (5 papers, 2014 to 2023). "For example, STK25 is important in lipid metabolism associated with liver, muscle, and adipose tissues, and MST3 is associated with glucose metabolism in the liver or glucose and insulin homeostasis in a Type 2 diabetes mouse model." (PMID 36653023, 2023). "Moreover, in type 2 diabetic patients, STK25 mRNA levels are significantly elevated in skeletal muscle, compared with healthy volunteers with normal glucose tolerance." (PMID 29996891, 2018). "Moreover, STK25 mRNA levels were higher in the skeletal muscle of individuals with type 2 diabetes than in healthy volunteers." (PMID 27981357, 2017). "STK25 emerges as a new regulator of the complex interplay between lipid storage, mitochondrial energetics and insulin action in skeletal muscle, highlighting the potential of STK25 antagonists for type 2 diabetes treatment." (PMID 27981357, 2017). "Consequently, STK25 is a potential target for the treatment of type 2 diabetes." (PMID 29996891, 2018).
Hyperinsulinemia (4 papers, 2020 to 2025). An increased concentration of insulin in the blood. "Additionally, ASOs targeting serine/threonine protein kinase 25 (Stk25) effectively reversed systemic hyperglycemia and hyperinsulinemia induced by a high-fat diet." (PMID 40438258, 2025). "Notably, although the fasting blood glucose levels remained similar in Stk25–/– and WT mice in this study, Stk25-KO mice exhibited suppressed hyperinsulinemia and an increase in whole-body glucose tolerance and insulin sensitivity at the end of the high-fat feeding period." (PMID 33170807, 2020). "Furthermore, the in vivo inactivation of STK25 and MST3 has been shown to effectively hinder the initiation and aggravation of NAFLD in obese mice, and to dampen the development of diet-induced systemic hyperinsulinemia." (PMID 37864157, 2023). "In agreement with our earlier studies in Stk25–/– and Mst3 ASO-treated mice, we found here that the development of high-fat diet-induced hyperinsulinemia was diminished in all groups lacking STK25, MST3, or STK25/MST3." (PMID 40983918, 2025).
colon cancer (3 papers, 2022 to 2023). "High expression of LIMK1 and STK25 is associated with poor prognosis in colon cancer patients." (PMID 35265128, 2022). "Overexpression of LIMK1 and STK25 plays a role in promoting cell proliferation and invasion in colon cancer tissues and cells." (PMID 35265128, 2022). "Immunohistochemical results showed that the positive rate of STK25 in colon cancer tissues was higher than that in para-cancer tissues." (PMID 35265128, 2022). "LIMK1 can mediate the proliferation, invasion, migration, and EMT of colon cancer cells through its interaction with STK25." (PMID 35265128, 2022). "The correlation between STK25 expression level and prognosis of colon cancer patients was analyzed by TCGA data." (PMID 35265128, 2022). "Transwell assay showed that knockdown of STK25 inhibited the migration of colon cancer cells." (PMID 35265128, 2022). "Furthermore, STK25 was mainly expressed in the cytoplasm of colon cancer tissues, which was significantly stronger than that of para-cancer tissues." (PMID 35265128, 2022). "The effect of LIMK1 and STK25 on the malignant progression of colon cancer was analyzed." (PMID 35265128, 2022). "This study detected a high expression of STK25 in colon cancer." (PMID 35265128, 2022). "In this study, LIMK1 can interact with STK25 to promote the EMT process in colon cancer." (PMID 35265128, 2022). "LIMK1 interacted with STK25 and was highly expressed in colon cancer." (PMID 35265128, 2022). "This study analyzed the expression and biological role of LIMK1 and STK25 in colon cancer." (PMID 35265128, 2022). "The LIMK1 and STK25 pathways may be new therapeutic targets for colon cancer." (PMID 35265128, 2022). "LIMK1 is highly expressed by colon cancer tissues, and inhibiting the expression of LIMK1 can reduce the proliferation, invasion and epithelial–mesenchymal transition of colon cancer cells by interacting with STK25." (PMID 36836593, 2023). "Cotransfection of LIMK1 and STK25 promotes the malignant progression and EMT of colon cancer." (PMID 35265128, 2022).